LIF (LIF interleukin 6 family cytokine)
Diseases named in the same sentence as LIF in open-access papers (continued):
Sharing a sentence is not in itself a finding about the gene and the disease.
Cachexia (continued). "In conclusion, the role of CRC cells is related to the production of classic cachexia-inducing factors (e.g., PIF, IL-6 and IL-6R, TNF-α, IL-1β, IL-1R1, and LIF), as well as novel factors known as “cachexokines”." (PMID 33557173, 2021). "IL-6 family cytokines other than LIF, which include IL-6, IL-11, and CNTF, were also reported as cachexia-inducing factors." (PMID 30410674, 2018). "Inflammatory cytokines derived from cancer cells and host immune cells, including interleukin (IL)-1, IL-6, tumor necrosis factor (TNF)-α, and leukemia inhibitory factor (LIF), are involved in the development of cancer anorexia-cachexia." (PMID 28249026, 2017). "IL-6 and other gp130 ligands such as LIF and CNTF are thought to mediate cachexia through a combination of anorexia, lipid catabolism, insulin resistance, and effects on protein synthesis and degradation." (PMID 21799891, 2011). "This study demonstrates the systemic effect of LIF on cachexia, and reveals that LIF overexpression disrupts hepatic de novo lipogenesis via the STAT3/PPARα axis as an important underlying mechanism." (PMID 38245529, 2024). "Although LIF plays a significant role in cachexia, the pathological process of cachexia is not achieved by LIF alone." (PMID 35740622, 2022). "It has been well-documented that a wide variety of cytokines can induce cachexia after prolonged production via multiple mechanisms, and these cytokines include TNF-α, IL-6, leukemia inhibitory factor (LIF), ciliary neurotrophic factor (CNTF) and interferon-γ (IFN-γ)." (PMID 26064446, 2015). "The other cytokines we observed increased in C26 mice that might also play a role in muscle wasting include IL-6-family ligands such as LIF, as well as TNF-a, IFN-gamma, all of which can induce cachexia independently." (PMID 21799891, 2011). "Importantly, results from this study suggest that LIF-induced functional changes in the liver, including its metabolic changes, contribute to LIF-induced cachexia; blocking the LIF signaling in the liver by liver-specific LIFR knockout partially abolished LIF overexpression-induced cachexia in mice." (PMID 38245529, 2024). "Meanwhile, LIF plays a non-negligible role in adipocyte alterations in cachexia, which could bind to LIFR to exert their effects on adipocytes by activating the JAK/STAT and MAPK (ERK1/2) signaling pathways." (PMID 35740622, 2022). "Mouse models engrafted with high LIF-secreting hematopoietic cells were seen to develop a fatal cachexia phenotype, and non-human primates injected with high doses of recombinant LIF experienced rapid loss of subcutaneous adipose, which resolved when treatment was terminated." (PMID 35204717, 2022). "Unfortunately, no study has yet addressed the impact of LIF on cachexia in PDAC models." (PMID 33630157, 2021). "Taken together, these results demonstrate that LIF overexpression in mice inhibits hepatic de novo lipogenesis, which may contribute to the decreased levels of small LC-TGs in the serum and liver tissues in TgLC mice with TAM injection and C26 tumor-bearing mice that develop cachexia." (PMID 38245529, 2024). "However, the relationship between LIF and IFN-γ remains unclear in cachexia." (PMID 35740622, 2022). "It is worth noting that in TAM-injected TgLC mice with LIF overexpression, no significant change in BHB levels was observed during cachexia development, indicating that LIF does not play an obvious role in ketogenesis during cachexia development." (PMID 38245529, 2024).
glioblastoma (27 papers, 2011 to 2025). The most malignant astrocytic tumor (WHO grade IV). "In a study of glioblastoma, the presence of high levels of LIF in the tumor microenvironment (TME) was associated with an increased number of tumor-associated macrophages (TAMs)." (PMID 34395259, 2021). "To determine whether activation of Gq-coupled receptors in astrocytes can similarly stimulate the release of LIF and IL-6, we screened for the presence of functional Gq-linked receptors in two glioblastoma/astrocytoma cell lines, U87-MG and 1321-N1." (PMID 39684791, 2024). "The strong stimulation of LIF secretion by bradykinin in both primary astrocytes and glioblastoma/astrocytoma cell lines prompted us to examine the involvement of specific bradykinin receptor subtypes." (PMID 39684791, 2024). "One such cytokine is transforming growth factor (TGF)-β, which is highly overexpressed in glioblastoma where it induces expression of the cytokine leukemia inhibitory factor (LIF) to consequently activate JAK/STAT3 to prevent differentiation of the GSCs." (PMID 33498872, 2021). "LIF-induced immunosuppression has been recently demonstrated in prostate cancer cells and glioblastoma." (PMID 34395259, 2021). "Two previous studies have reported the induction of LIF mRNA and/or protein by TGFβ in Schwann cells and glioblastoma and shown this upregulation to be Smad-dependant by binding to a Smad binding element in LIF promoter." (PMID 25885043, 2015). "Furthermore, it has been shown that BM-MSCs promote senescence of the U87 glioblastoma cell line by inducing changes in cell morphology and by increasing the production of cytokines (IL-6, IL-8, leukemia inhibitory factor (LIF), CCL2/MCP-1, and CXCL2)." (PMID 38607056, 2024). "Moreover, LLL12 induces apoptosis in medulloblastoma and glioblastoma cells and was also able to inhibit colony formation, wound healing and decreased IL-6 and LIF secretion." (PMID 22530037, 2012). "A recent study has shown that LIF regulates CD8+ T cell tumor infiltration by repressing CXCL9 expression in tumor-associated macrophages, and blocking LIF enhances T cell infiltration, improving responses to anti-PD1 therapy in glioblastoma and ovarian cancer models." (PMID 39857986, 2025). "Examples of such paracrine interactions include glioblastoma, where cancer cells expressing mutant EGFR stimulate the growth of tumor cells with WT EGFR through cytokine secretion (IL‐6 and LIF)." (PMID 37418588, 2024). "Their data showed that miR-93 was downregulated in human glioblastoma cell lines, and restoration of miR-93 levels in glioblastoma cells led to a decreased expression of an array of inflammatory genes (HIF-1α, MAP3K2, IL-6, G-CSF, IL-8, LIF, and IL-1β)." (PMID 38239396, 2023). "Key gliogenic genes having the ability to control oncogenesis in glioblastoma cells: p300, BMP, PAX6, HOPX, NRSF/REST, LIF, and TGF beta.TGF beta: It has a very important gliogenic effect." (PMID 35538578, 2022). "This study identifies key gliogenic genes having the ability to control oncogenesis in glioblastoma cells, including p300, BMP, PAX6, HOPX, NRSF/REST, LIF, and TGF beta." (PMID 35538578, 2022). "Additional pathways supporting PMT of glioblastoma cells are induced by hypoxia, necrosis, 17β-estradiol, CXCL12, C5a, bradykinin, and the interleukin (IL)-6 family cytokines, including IL-6, leukemia-inhibitory factor (LIF), and oncostatin M (OSM)." (PMID 39857717, 2025). "There, genes with a higher expression in glioblastoma compared to astrocytoma were VEGFA, 4EBP1, CCL2, PLAU (uPA), CXCL8 (IL8), CXCL10 (IP10), CASP8, HGF, LIF, CD40, CDCp1, TNFRSF11B (OPG), CD274 (PD-L1), IL6, CXCL1, CCL20 (MIP3α), CCL8 (MCP2), CD244, MMP1, TNFRSF9, CXCL6, MMP10, FGF5)." (PMID 35301393, 2022).
glioblastoma (continued). "Studies showed that TGF-β regulates the cancer stem cell self-renewal and differentiation properties via inducing leukemia inhibitory factor (LIF) and IL-11 activation of the JAK/STAT pathway and STAT3 phosphorylation in glioblastoma and colon cancer, respectively." (PMID 30944375, 2019). "This study identifies key gliogenic genes/signaling pathways having the ability to control oncogenesis in glioblastoma cells including p300, BMP, PAX6 (anti-GBM override), HOPX (tumor suppressive + differentiation), NRSF/REST (astrcytogenic but capable of playing oncogenic role), LIF, and TGF beta." (PMID 35538578, 2022).
endometriosis (26 papers, 2007 to 2026). The growth of functional endometrial tissue in anatomic sites outside the uterine body. "Additional recent confirmatory data supporting the secretome theory include the association of endometriosis with exosomes that increase invasion and migration, and the persistence of LIF into the menstrual phase in humans." (PMID 38728307, 2024). "Our results appose these findings, potentially providing insight into a novel endometriosis associated LIF pathway whereby LIF intervention is reducing immunoregulatory phenotypes and promoting a potential cytotoxic response." (PMID 37033980, 2023). "Molecular mechanisms underlying the impaired uterine receptivity in endometriosis are mainly increased inflammatory cytokine and abnormal implantation markers, with LIF and HOXA10 playing important roles in embryo implantation and development." (PMID 35273494, 2022). "Elevated levels of LIF were noted in ectopic tissues, especially during the secretory phase, suggesting a role in the inflammatory milieu of endometriosis." (PMID 40649777, 2025). "In endometriosis, aberrant expression of endometrial genes, including homeobox (Hox) genes, integrins, and leukemia inhibitory factor (LIF), affects endometrial receptivity." (PMID 39338174, 2024). "Due to limited access to PF samples from healthy controls only endometriosis LIF expression in the PF was shown." (PMID 37033980, 2023). "Our findings are in accordance with other endometriosis literature identifying downstream LIF targets NANOG, OCT-3/4, and SOX2 to be elevated in ectopic lesions compared to control endometrium." (PMID 37033980, 2023). "Our findings identify LIF in the lesion microenvironment, with detection of LIF in the PF and protein extracts of both ectopic and eutopic endometriosis tissues." (PMID 37033980, 2023). "While we present this data to document LIF presence in endometriosis PF samples, future studies are needed to provide a comparison between endometriosis and control samples." (PMID 37033980, 2023). "Previous reports have analyzed LIF within the endometrial tissue of endometriosis patients as it pertains to fertility status, however it has yet to be identified within the ectopic lesion." (PMID 37033980, 2023). "Together, these results indicate that ectopic LIF production is rescued in endometriosis patients, highlighting a dysregulation of LIF between endometriosis tissues." (PMID 37033980, 2023). "Despite this limitation, the trend of reduced immunoregulatory phenotypes was consistent between LIF treatments supporting its role as an immunomodulator within endometriosis." (PMID 37033980, 2023). "Spatial localization of LIF in endometriosis patients and control tissues, as provided by our IHC data, further corroborates that LIF is present in ectopic lesions with LIF staining localized to the luminal and glandular epithelium." (PMID 37033980, 2023). "In conclusion, this study demonstrates that LIF is present in ectopic endometriosis lesions and provides insight to the potential contributions it has to endometriosis pathophysiology." (PMID 37033980, 2023). "Low-dose aspirin is thought to improve endometrial progesterone resistance during the window period in endometriosis patients, increasing the expression of the receptivity-related molecule LIF and increasing endometrial receptivity." (PMID 36524127, 2022). "Taken together, in the endometrium resected from rats with endometriosis, metformin increased LIF protein and mRNA expression, and enhanced HOXA10 protein expression dependent on metformin dosage." (PMID 35273494, 2022). "This study also revealed that improvement in endometrial receptivity in rats with endometriosis treated with metformin also correlated with an increase in the expression of the implantation markers, LIF and HOXA10, within the endometrium." (PMID 35273494, 2022). "There is a decrease in LIF expression in the endometrium of both hydrosalpinx patients and endometriosis patients." (PMID 35012573, 2022).
endometriosis (continued). "Specifically, the gland-specific transcription factor Forkhead box A2 (FOXA2) is required for LIF expression in mice, but it is decreased in endometrium from women with endometriosis." (PMID 31387263, 2019). "Although LIF expression is induced by E2 in the endometrium, and estrogenic activity is increased in endometriosis, LIF levels have been reported to be decreased in the glandular epithelium of women with this disease." (PMID 31387263, 2019). "Another important endometrial receptivity marker that seems to be impaired in theendometrium of individuals with endometriosis is LIF." (PMID 28967712, 2017). "Notably, elevated LIF levels and increased mast cell activity in ectopic tissues underscore the inflammatory landscape of endometriosis." (PMID 40649777, 2025). "Nerves in the endometriosis lesion release chemicals like colony-stimulating factor-1 (CSF-1), chemokine ligand 2 (CCL-2), leukemia inhibitory factor (LIF), and pancreatitis-associated protein III (PAP-III), which induce the migration of macrophages toward the nerve ending." (PMID 40747182, 2025). "Endometriosis has been shown to have elevated LIF in the peritoneal fluid." (PMID 38728307, 2024). "Thus, we sought to explore the implications of LIF production within ectopic lesions on endometriosis pathophysiology." (PMID 37033980, 2023). "Finally, LIF treatment in a syngeneic mouse model of endometriosis induced both local and peripheral alterations to immune cell phenotypes, ultimately reducing immunoregulatory CD206+ small peritoneal macrophages and T regulatory cells." (PMID 37033980, 2023). "LIF has been shown to promote tumor growth and vascularization in cancer, thus we sought to determine if those effects were withstanding in our syngeneic mouse model of endometriosis." (PMID 37033980, 2023). "Additionally, these are varying endothelial cell types, thus further investigation of LIF specifically on endometriotic endothelial cells is needed to elucidate its role within endometriosis." (PMID 37033980, 2023). "In vitro treatment of endometriosis representative cell lines (12Z and hESC) with LIF increased production of immune-recruiting cytokines (MCP-1, MCP-3) and the angiogenic factor, VEGF, as well as stimulated tube formation in human umbilical vein endothelial cells (HUVECs)." (PMID 37033980, 2023). "Our customized RT qPCR array included both CNTF and OSM to determine whether IL-6 family proteins or LIF specifically were dysregulated within endometriosis." (PMID 37033980, 2023). "Additionally, as LIF can promote vascularization and proliferation, we sought to determine the effects of LIF on endometriosis lesion representative cell lines." (PMID 37033980, 2023). "However, when patients were stratified by menstrual phase, there was a significant difference between ectopic and eutopic LIF staining (p<0.001) illustrating a dysregulation in the production of LIF within endometriosis patients during the secretory phase." (PMID 37033980, 2023). "Finally, the E2-responsive cytokine LIF, required for fertility in mice and women, is both decreased generally in endometrium from women with endometriosis and specifically correlated with failure to achieve pregnancy in women with the disease." (PMID 31387263, 2019). "The decrease in LIF secretion from glands may also be due to intrinsic gland dysfunction in endometriosis." (PMID 31387263, 2019). "The aim of this study was to compare the endometrial expression of milk fatglobule-EGF factor 8 (MFG-E8), its receptor integrin αvβ3, andleukemia inhibitory factor (LIF) in patients with endometriosis andinfertility and in healthy fertile patients during the window ofimplantation." (PMID 28967712, 2017).
endometriosis (continued). "Studies evaluating gene expression in embryo implantation, endometriosis and ovarian cancer have all found altered expression of LIF, and other genetic and epigenetic changes, such as CD44 and miR 99a-5p, supporting our hypothesis that the uterine secretome is important in all these processes." (PMID 38728307, 2024). "Gene expression studies in embryo implantation, endometriosis and ovarian cancer metastasis have all found altered expression of LIF, and other genes such as CD44 and miR 99a-5p, supporting our hypothesis that the uterine secretome is important in benign and malignant processes." (PMID 38728307, 2024). "Thus, further investigation is required to confirm whether the upregulation of NANOG is due specifically to LIF signaling or other mediators in endometriosis." (PMID 37033980, 2023). "PF samples from healthy, fertile controls could not be obtained due to logistical difficulties; however, demonstrating the presence of LIF in the PF of women with endometriosis represents a novel finding in and of itself as it demonstrates that LIF is present in the endometriotic microenvironment." (PMID 37033980, 2023). "Thus, the aims of this study were to first to examine VEGF and MMP-9 expression from endometriotic implants in rats with endometriosis and second to investigate the effects of metformin on endometrial receptivity through regulation of LIF and HOXA10 expression." (PMID 35273494, 2022). "This could be due to increased inflammatory factors in endometriosis that can suppress LIF." (PMID 31387263, 2019). "Validation in gestational epithelial endometriosis organoids showed upregulation of IGF2 and NR2F2, and downregulation of LIF." (PMID 42282918, 2026). "Our next step was to gain spatial understanding of LIF within the lesion microenvironment, thus, IHC was performed on a TMA of endometrioma and control endometrium samples (endometriosis matched; n=19, controls; n=21)." (PMID 37033980, 2023). "The protein and mRNA expression of the vascular endothelial growth factor (VEGF), matrix metalloproteinase-9 (MMP-9), the endometrial receptivity markers, LIF and HOXA10, were measured in the endometrium of rats with endometriosis." (PMID 35273494, 2022). "Metformin also significantly upregulated LIF and HOXA10 expression in endometrium from rats with endometriosis." (PMID 35273494, 2022). "SPP1, LIF, TCN1 and CLDN4 were common to adenomyosis and healthy groups of genes, while ANXA2, EDNR8, MMP26, DEPP1, ABCC3, CDA and SLC1A1 were common to endometriosis and healthy groups." (PMID 32933042, 2020). "Notably, several studies report decreased levels of proteins such as LIF, ARID1A (AT-rich interaction domain 1A), and HNF4A (hepatocyte nuclear factor 4 alpha) in the endometriosis tissues." (PMID 40649777, 2025). "Additionally, melatonin has been shown to increase the expression of genes like LIF, HOXA10, and HOXA11 in endometriosis mice." (PMID 39409719, 2024). "Taken together, the expression of LIF and HOXA10 in the endometrium may affect receptivity of endometrium in women with endometriosis." (PMID 35273494, 2022). "In addition, the leukemia inhibitor factor (LIF) and HOXA10 genes are also distinguishing markers of endometriosis (decrease) and endometrial receptivity (increase)." (PMID 35273494, 2022). "A number of implantation markers such as αvβ3 integrin, LIF, homeobox A10 (HOXA10) and HOXA11 are aberrantly expressed in patients with endometriosis and may contribute to infertility in some women with endometriosis." (PMID 34149619, 2021). "We believe that the beneficial effects of metformin in the treatment of endometriosis is a result of combination of diminishment endometrial lesions through suppression of VEGF and MMP9, and improvement of uterus conditions for implantation via LIF upregulation." (PMID 35273494, 2022).
endometriosis (continued). "Thus, though increased estrogenic activity promotes harmful inflammation and cell proliferation in endometriosis, it apparently fails to properly induce LIF expression." (PMID 31387263, 2019).